G6PD (glucose-6-phosphate dehydrogenase)
Diseases named in the same sentence as G6PD in open-access papers (continued):
Sharing a sentence is not in itself a finding about the gene and the disease.
thalassemia (continued). "In Argentina, beta-thalassemia was detected in 4.8% of the G6PD-deficient subjects, and the concurrence of haemoglobin S and congenital sphaerocytosis with G6PDd was detected in 4 and 2% of the subjects, respectively." (PMID 24568147, 2014). "A comparable convergent evolution between protecting G6PD mutations and thalassemia or sickle cell anemia has been proposed." (PMID 17637841, 2007). "Genotyping defined G6PD (G6PD c.202T allele), haemoglobin S (HbS), and α-thalassaemia status." (PMID 37858129, 2023). "The release of MPs containing hemichromes was already described in oxidized erythrocytes, in parasitized RBCs, and in different hematological diseases characterized by hemichrome formation such as thalassemias and G6PD-deficient RBCs following oxidant treatment." (PMID 32824055, 2020). "In addition, there were some differences of the distribution of thalassemia and G6PD mutations among eight counties in Meizhou." (PMID 31793705, 2020). "The severity of anemia in SCD may also be affected by the co-inheritance of other SCD modifying polymorphisms, including the α-thalassaemia 3·7 deletion and glucose-6-phosphate dehydrogenase (G6PD) deficiency." (PMID 30056060, 2018). "The genetic resistance toward malaria infections found in sickle cell trait, thalassemia trait, and G6PD-deficient individuals has partially been attributed to the sensitivity of their RBC to induce PS exposure and erypotosis upon infection with as a result accelerated clearance of infected RBCs." (PMID 28210260, 2017). "This discrepancy may lie in the types of G6PD deficiencies and thalassemias involved in these studies." (PMID 28531196, 2017). "Other inherited blood disorders occurring regionally, such as the thalassemias, HbE and Glucose-6-Phosphate Dehydrogenase may be involved in determining susceptibility to P. vivax infection (and P. falciparum parasite density)." (PMID 19060954, 2008). "Of the HHA types, G6PD traits had the highest incidence at birth, while thalassemias had the lowest incidence at birth over the 22-year span." (PMID 40982566, 2025). "Overall, estimated YLD rates were highest for sickle cell traits compared to Thalassemia and G6PD, while YLD rates were lowest for G6PD traits." (PMID 40982566, 2025). "Other HHA (e.g., thalassemias and G6PD) contributed to fewer deaths in the 22-year span and had stable or decreasing mortality over time." (PMID 40982566, 2025). "Briefly, in the tafenoquine group, three serious adverse events occurred in G6PD normal patients, including one case of thalassaemia trait with blood transfusion, one case of leptospirosis and one case of scrub typhus." (PMID 40274286, 2025). "By 2021, the age-standardized death rate had decreased for G6PD to 17.49 (95% UI 10.90 – 30.61), or was fairly consistent for SCD 0.52 deaths (95% UI 0.31 – 0.96) and thalassemias caused 0.21 (95% UI 0.14 – 0.30), per 100,000 population compared to 2000." (PMID 40982566, 2025). "Of the seven categories of HHA identified by the GBD studies, SCD has the most severe pathophysiology, resulting in painful crises characterized by extreme pain and lower life expectancy compared to G6PD and thalassemias." (PMID 40982566, 2025). "G6PD status was established in 1120/1137 (98.5%) children; heterozygous α-thalassaemia was found in a little under half of children and homozygous α-thalassaemia in < 10%." (PMID 37858129, 2023). "Extending our analysis of this study, we sought to determine the independent effects of several factors, including G6PD and sickle cell status, thalassaemia, and SLDPQ on the course of haemoglobin over time." (PMID 37858129, 2023). "Their reasoning behind the study was that they would be able to assess how CBF in patients with SCD was affected by three polymorphisms: glucose-6-phosphate dehydrogenase (G6PD), α-thalassemia, and the Hp genotype." (PMID 35052484, 2022).
thalassemia (continued). "Meanwhile, recipient requests for sperm donor carrier screening for G6PD genes were only second to that for thalassemia." (PMID 36204111, 2022). "Characteristics of Malawi Sickle Surveillance Study participants in the Central region of Malawi, 2018, stratified by sickle cell, α-thalassemia, and G6PD status." (PMID 34335138, 2021). "G6PD status was the most consistent determinant of the degree of acute hemolytic anemia and recovery, whereas thalassemia and baseline parasite count were important contributors." (PMID 31549159, 2019). "Genomic studies conducted in SCD in Tanzania have already reported variability in prevalence of and co-existence of genomic loci that influence HbF, α-thalassemia, and G6PD levels." (PMID 30459954, 2018). "Note, however, that the signals of association are moderate compared with those for sickle cell, α-thalassemia, and G6PD." (PMID 28541483, 2017). "PCR primers and RFLP conditions for G6PD variants common in Southwest Sumba Regency and PCR primers for detecting SAO, HbE and α thalassemia." (PMID 26894297, 2016). "The contributions of the new loci tend to be greater than the established effects of ABO blood group (0.2%), α-thalassemia (0.3%), and G6PD (0.5%), making them enticing targets for further investigation, including functional studies." (PMID 25805752, 2015). "Of the 22.2% of variation explained overall, age, sex, and ethnicity accounted for 47.2%, and the established gene candidates accounted for another 33.6% (HbAS, 28.6%; G6PD, 2.2%; α-thalassemia, 1.5%, ABO blood group, 1.2%)." (PMID 25805752, 2015). "While awareness about SCD and G6PD was reasonably high, only about half of the participants reported awareness about thalassemia." (PMID 24742222, 2014). "The study found that males had statistically significant increased awareness of SCD and G6PD than females, while females had increased awareness about thalassemia than males." (PMID 24742222, 2014). "Males had significantly increased awareness about SCD and G6PD than females, while females had increased awareness about thalassemia than males." (PMID 24742222, 2014). "In total, 100.0% (464/464) and 95.9% (445/464) of the samples were successfully genotyped for G6PD and α+-thalassaemia status, respectively." (PMID 19460160, 2009). "Furthermore, the male-to-female birth incidence ratios for HHA sub-types, including SCD, thalassemias, and G6PD, have remained relatively unchanged over time." (PMID 40982566, 2025). "In addition, our sperm bank has increased the screening of thalassemia and G6PD for qualified sperm donors." (PMID 36204111, 2022). "Primary screening for thalassemia and G6PD with the whole blood of 3231 sperm donors." (PMID 36204111, 2022). "Moreover, RDB technology is more mature and has been widely used in the molecular diagnosis of genetic diseases such as thalassemia and G6PD in China7." (PMID 31382905, 2019). "A further difficulty in detecting individuals carrying both alpha and beta thalassaemia may arise from the variation in another protein: glucose-6-phosphate dehydrogenase (G6PD)." (PMID 25521998, 2015). "Genetic evaluations confirmed the absence of cystic fibrosis mutations and normal karyotypes; fragile X carrier screening revealed normal results, no mutations in coagulation genes (factors V, II, or MTHFR), and no thalassemia or glucose-6-phosphate dehydrogenase (G6PD) mutations." (PMID 41492634, 2025). "In addition, due to the fact that hemolysis in patients with thalassemia can stimulate the body to produce a large number of red blood cells, some researchers have found that the G6PD activity in patients with thalassemia is higher than that in healthy individuals." (PMID 39076173, 2024).
thalassemia (continued). "Children with SCD were followed up, but parents of children with other inherited blood disorders were not contacted, as α-thalassemia trait does not require specific medical intervention, and primaquine, the main source of morbidity for G6PD deficient children, is not commonly used in Malawi." (PMID 34335138, 2021). "Similarly, restricting the dataset to children without two other known polymorphisms (the α-thalassemia 3.7 kb deletion or glucose-6-phosphate dehydrogenase deficiency caused by the common African variant (G6PD A-)), had little effect on the results." (PMID 30044224, 2018). "Most of the YLDs for thalassemias, SCD, and G6PD occurred collectively among children under age 10 in the WHO Africa region." (PMID 40982566, 2025). "Sickle cell anaemia prevalence of under 1%, homozygous or thalassaemia trait of 4.4% in WIRA and G6PD prevalence (partial and full defect) of 0.8% up to 19.3% in pregnant women have been reported in the country." (PMID 36303165, 2022). "The possibility of reduced susceptibility of parasites to ACT in G6PD deficient patients could not also be ruled out since in a study with α-thalassemia patients, it was hypothesized that the infected variant erythrocytes could not accumulate as much drug as infected normal erythrocytes." (PMID 21092137, 2010). "This differs greatly as priapism has been frequently reported in patients with other chronic hemoglobinopathies such as sickle cell disease, thalassemia, and G6PD with and without splenectomy." (PMID 37197195, 2023). "Glucose-6 phosphate dehydrogenase (G6PD) activity was normal, thalassemia screen was negative, and dengue NS1 antigen was negative." (PMID 27613607, 2016). "The study herein reported was not designed a priori to detail the haematological responses; thus, key haematological parameters like the mean corpuscular volume, reticulocyte counts, iron metabolic parameters, G6PD status, presence of thalassaemia and ovalocytosis were not tested." (PMID 23777546, 2013). "Furthermore, a majority of children did not have G6PD (72%) nor α-thalassemia (60%)." (PMID 31760954, 2019).
haemolytic anaemia (72 papers, 2009 to 2026). "Analogies can be made with G6PD, a gene where dysfunctional variation confers a selective advantage in the presence of plasmodium falciparum, but otherwise increases risk of haemolytic anaemia." (PMID 41428259, 2025). "In G6PD-deficient patients with acute malaria, the disease itself causes haemolytic anaemia, and the consequent preferential loss of older erythrocytes ameliorates the adverse impact of oxidant drugs." (PMID 38319064, 2024). "In the current study, seven patients had primaquine-related acute haemolytic anaemia, six of whom were G6PD deficient." (PMID 38365417, 2024). "Primaquine administration is associated with toxicity manifested as haemolytic anaemia and is contraindicated for individuals deficient of the glucose-6-phosphate dehydrogenase (G6PD) enzyme or pregnant women." (PMID 37312065, 2023). "We conducted an NF safety review of all haemolytic anaemia reports available from a variety of sources since the 1950s, when it first became available, with an emphasis on those confirmed in G6PD-deficient individuals." (PMID 35529053, 2022). "G6PD deficiency triggers haemolytic anaemia in states of oxidative stress because deficient erythrocytes contain low levels of NADPH, which is required for maintaining cellular redox homeostasis through glutathione recycling." (PMID 36038921, 2022). "Even though G6PD deficiency provides clinical protection against Plasmodium spp., G6PD-deficient patients are susceptible to haemolytic anaemia when exposed to active and toxic metabolites of primaquine (PQ) and tafenoquine (TQ)." (PMID 36038921, 2022). "Two other cases in ≥75 year-old females in Europe had received glimepiride for type 2 diabetes, a sulfonylurea drug associated with a haemolytic risk in G6PD-deficient patients and post-marketing reports of haemolytic anaemia in non-G6PD-deficient patients." (PMID 35529053, 2022). "A deficiency in the enzyme G6PD by the G6PD MahidolG487A mutation exhibits a statistically significant correlation with haemolytic anaemia during malaria infection." (PMID 36038921, 2022). "In the beginning of G6PD mutation screening, the study of G6PD mutations focused only on the detection of the G6PD Viangchan mutation or identified the G6PD mutation only in males that presented with severe haemolytic anaemia." (PMID 33413378, 2021). "These variations were clinically important because they can attenuate G6PD activity, thus indicating the risk of drug-induced acute haemolytic anaemia." (PMID 34306260, 2021). "Acute haemolytic anaemia has been reported in G6PD-deficient individuals after administration of certain antimalarial drugs, including dapsone, methylene blue, and 8-aminoquinolines (primaquine and tafenoquine)." (PMID 34353361, 2021). "In G6PD deficient patients, acute haemolytic anaemia occurred with chloroquine and HCQ treatment, and methemoglobinemia was observed with ceftriaxone treatment." (PMID 34306260, 2021). "Primaquine (PQ) is a classical example of oxidative drugs that induce acute haemolytic anaemia due to the suboptimal activity of G6PD which associated with the presence of G6PD SNP(s)." (PMID 30819192, 2019). "PQ is known to be effective against P. falciparum gametocytes but is not widely used in endemic areas because of concerns on the risk of haemolytic anaemia in individuals with glucose-6-phosphate dehydrogenase (G6PD) deficiency." (PMID 31600221, 2019). "Haemolytic anaemia in G6PD-deficient individuals can range from mild to life-threatening conditions." (PMID 30367627, 2018). "The widespread use of primaquine has been limited due to its potential to induce haemolytic anaemia in glucose-6-phosphate dehydrogenase (G6PD)-deficient individuals." (PMID 30367627, 2018). "The antimalarial drug primaquine, which is of great practical importance for the treatment and elimination of P. vivax malaria, can precipitate severe and sometimes fatal haemolytic anaemia in G6PD-deficient individuals." (PMID 28067620, 2017).
haemolytic anaemia (continued). "Nevertheless, at therapeutic dose against the hypnozoites, primaquine can cause a self-limiting to severe haemolytic anaemia in patients with an inborn deficiency of enzyme-G6PD." (PMID 28535765, 2017). "Its numerous limitations as a drug contribute to this, but the potential risk of inducing haemolytic anaemia in patients with a deficiency in glucose-6-phosphate dehydrogenase (G6PDd) enzyme activity levels is the primary limitation." (PMID 28376871, 2017). "Pregnant and lactating women cannot receive primaquine, due to risks of haemolytic anaemia in glucose-6-phosphate dehydrogenase (G6PD) deficient foetuses." (PMID 26537247, 2015). "Primaquine was licenced for anti-relapse therapy in 1952 and became available despite threatening patients having an inborn deficiency of glucose-6-phosphate dehydrogenase (G6PD) with acute haemolytic anaemia." (PMID 25943156, 2015). "Primaquine causes a mild to severe acute haemolytic anaemia in patients having an inborn deficiency of G6PD." (PMID 25943156, 2015). "The clinical value of this class is compromised by the toxic side effects, however, which include methemoglobinaemia and haemolytic anaemia in patients with deficiency in glucose-6-phosphate dehydrogenase (G6PD) activity." (PMID 24731238, 2014). "Phenolic metabolites of PQ are the most likely candidates for such activity, and have frequently been linked to the associated haemolytic anaemia observed in G6PD-deficient individuals after PQ therapy." (PMID 23782898, 2013). "Unfortunately, the use of 8-AQs is limited by their tendency to cause haemolytic anaemia in individuals with a genetic deficiency in glucose-6-phosphate dehydrogenase (G6PD), an enzyme implicated in the body’s defence against oxidative stress." (PMID 22856549, 2012). "In Rwanda, G6PD-deficient subjects treated with CDA had a significantly higher risk for haemolytic anaemia than those treated with amodiaquine and artesunate." (PMID 22546009, 2012). "Unfortunately, in some studies heterozygous females have been labelled as G6PD deficient, and grouped together with G6PD deficient hemizygous males, which has compromised assessments of the clinical severity of acute haemolytic anaemia (AHA)." (PMID 23237606, 2012). "Fifteen class B G6PD variants were reported, presenting oxidant-induced acute haemolytic anaemia." (PMID 41953713, 2026). "The clinical course of acute haemolytic anaemia varies in duration and severity depending on many factors: first and foremost, drug dose, but also baseline haemoglobin level and other individual variables, including the G6PD variant itself." (PMID 39070600, 2024). "Of 16 G6PD-deficient or G6PD-intermediate patients who were administered tafenoquine, three (18·8%) completed day-5 follow-up, and one G6PD-deficient patient had signs of acute haemolytic anaemia but was already hospitalised as a precaution." (PMID 38365417, 2024). "However, a long-term PQ administration (15 mg daily for 14 days) in the G6PD-deficient individuals is associated with a high risk of acute haemolytic anaemia, and once weekly dosing for 8 weeks is recommended in these individuals." (PMID 38773528, 2024). "The main modification is the merger of variants formerly in class II and in class III into a single class B that comprises all the common polymorphic G6PD variants, all of which entail the risk of severe neonatal jaundice and of acute haemolytic anaemia triggered by fava beans or drugs." (PMID 39070600, 2024). "However, safety concern remains related to the acute haemolytic anaemia associated with a higher primaquine doses which will be required to clear the radical P. vivax and Plasmodium ovale in G6PD deficient individuals." (PMID 38062464, 2023). "Higher dosage of PQ is associated with acute haemolytic anaemia in G6PD deficient individuals." (PMID 38062464, 2023).